CTSL (cathepsin L)
Diseases named in the same sentence as CTSL in open-access papers (continued):
Sharing a sentence is not in itself a finding about the gene and the disease.
COVID-19 (continued). "However, preclinical and clinical evidence is required to assess whether cathepsin L inhibitors may show a benefit in COVID-19 treatment." (PMID 35871712, 2022). "In conclusion, we show that CTSL is highly expressed in normal tissues and increased in most cancers, and CD or m62A could inhibit its expression, suggesting the therapeutic potential of targeting CTSL for cancer and COVID-19 treatment." (PMID 35414771, 2022). "Thus, CTSL might play a major role in the susceptibility of lung cancer and glioma patients to SARS-CoV-2 uptake and COVID-19 severity." (PMID 35414771, 2022). "Thus CTSL may play a vital role in the susceptibility to SARS-CoV-2 entry and severity of COVID-19 clinical symptoms, particularly in lung cancer and in glioma patients." (PMID 35414771, 2022). "Therefore, cathepsin L inhibitors have been proposed as therapeutic options for COVID-19." (PMID 35871712, 2022). "Therefore, CTSL is a promising target for new anti-COVID-19 drug development." (PMID 33774649, 2021). "Interestingly, a CTSL inhibitor could efficiently block the entry of SARS-CoV-2 into cells, indicating a potential contribution of CTSL to the pathogenesis of COVID-19." (PMID 34876996, 2021). "Hence, CTSL is likely an important therapeutic target for COVID-19." (PMID 33774649, 2021). "Together, various studies have identified an important role of cysteine cathepsins in virion entry and suggest that inhibition of cathepsins, especially cathepsin L, could be an effective strategy for the search/development of new drugs for the treatment of COVID-19." (PMID 33137165, 2020). "Human cathepsin L (hCatL), a lysosomal cysteine protease, facilitates endosomal entry for SARS-CoV-2, making it a critical therapeutic target for COVID-19." (PMID 42014929, 2026). "The repurposing of known TMPRSS2 and CTSL/CTSB inhibitors can become an effective and safe treatment option for COVID-19." (PMID 37990007, 2023). "TMPRSS2 and ACE2 expression were upregulated in COVID-19 patients but BSG, CTSL, FURIN expression was higher in IPF patients, suggesting their role in increased myofibroblast expression in COVID-19." (PMID 36248845, 2022). "We then examined the relationship between TMPRSS2 and other targets for COVID-19 therapy, including ACE2, AXL, CTSL and FURIN." (PMID 35017320, 2022). "Cardiac injury can be triggered by a number of direct and indirect mechanisms including viral injury and the interplay with host cells (COVID-19 spike protein (S), ACE2 receptor, host serine protease TMPRSS2, cathepsin B, and cathepsin L)." (PMID 37386548, 2022). "This module included the NUPR1 stress response gene as well as CSTB, which is an inhibitor of cathepsins like CTSL and CTSB that are involved in COVID-19 viral entry." (PMID 35007307, 2022). "In contrast, in macrophage/monocyte and dendritic cells, the proportion co-expressing NRP1 with CTSL and FURIN was reduced in COVID-19 patients’ lungs." (PMID 35458567, 2022). "The CTSL and CTSL/CTSB levels were markedly higher in patients with COVID-19 than in healthy volunteers, while the CTSB level was unchanged in the patients." (PMID 33774649, 2021). "GSEA of the COVID-19 related gene sets revealed that both TMPRSS2 and CTSL belong to SARS top 50 geneshot AutoRIF along with SARS 133 Literature-Associated Genes from Geneshot GeneRIF." (PMID 34407143, 2021). "In HNECs treated with HMGB1 and OSM, upregulation of the COVID-19-related genes TMPRSS6, furin, and cathepsin L (CTSL) is observed." (PMID 34445093, 2021). "During the COVID-19 pandemic, it has been further demonstrated that SARS-CoV-2 can use CTSB and CTSL as well as TMPRSS2 for priming host cells." (PMID 34820418, 2021). "Recently, a relationship between CTSL and coronavirus (SARS-CoV-2) disease (COVID-19) has been reported." (PMID 34445307, 2021).
COVID-19 (continued). "IL-6 increases the severity of COVID-19 by rearranging the angiotensin-converting enzyme (ACE2) receptors and inducing macrophage cathepsin L. Cathepsin L of macrophage cleaves the S1 subunit of the coronavirus spike glycoprotein." (PMID 34475485, 2021). "Studies have also shown that compared with controls, the lung tissue of patients who died of COVID-19 had upregulated expression of proteins such as NPC1/2, CEACAM1, CTSL, EIF4E, and PABPN1, which involve virus-binding receptors, proteases, host mRNA degradation, and translation cessation." (PMID 38752128, 2024). "Only CTSL levels were significantly higher in diabetic patients than in non-diabetic patients and changed with the course of COVID-19." (PMID 39150053, 2024). "The cathepsin L cleavage site has been preserved in the SARS-CoV and COVID-19 S proteins." (PMID 39683724, 2024). "We found that only CTSL levels were significantly increased in diabetic patients compared to non-diabetic patients and varied during the course of COVID-19." (PMID 39150053, 2024). "Cathepsin L, in particular, appears to play a prominent role in the entry of SARS-CoV-2 into the cell and is therefore discussed as a pharmaceutical target against COVID-19." (PMID 36093380, 2022). "Cathepsin L has been reported to be overexpressed after infection with SARS-CoV-2, allowing further progression of infection and leading to a vicious cycle: the more cathepsin L is expressed, the more severe the progression of COVID-19." (PMID 35943189, 2022). "Increased levels of circulating cathepsin L were detected in patients with severe COVID-19 than in patients with non-severe COVID-19 or in healthy individuals." (PMID 36438831, 2022). "In the previous study, it has been revealed that only cathepsin L, and not calpain or cathepsin B, is participated in COVID-19 endocytosis entry." (PMID 34222852, 2021). "First, no investigation of circulating levels of CTSL in patients with COVID-19 had been reported before this study." (PMID 33774649, 2021). "With scatterplots, the relationship between S100A8 and CTSL genes and SARS-CoV-2 infection was suggested to be only negatively related to viral gene expression levels in high infections, and all COVID-19–related viral genes, especially N and ORF1ab genes, showed a positive relationship." (PMID 34497809, 2021). "Broadening the range of therapeutic targets for COVID-19 is important, and the effects of CTSL should not be underestimated." (PMID 33774649, 2021). "Although CTSL expression was detected in pancreatic cells from non-COVID-19 subjects, the expression levels in pancreatic cells from COVID-19 patients have not been reported." (PMID 35053020, 2021). "For patients with more severe symptoms (i.e. COVID-19 patients who were admitted to ICU), there was still a significant relationship between the four predictors and CTSL expression; however, these only accounted for 35.78% of the variance (adjusted R2 = 0.3578, p-value = 7.086–05)." (PMID 33633121, 2021). "With non-severe (non-ICU) COVID-19, there was increased expression of the viral entry gene (CTSL (p < 0.05)) and increased antiviral response genes (MX1 (p < 0.0001), SAMHD1 (p < 0.0001), TRIM25 (p < 0.01), IFITM3 (ns))." (PMID 33633121, 2021). "That reviewshowed how IL-6 increases the severity of COVID-19 by upregulating angiotensin-converting enzyme 2 (ACE2) receptors and induction of macrophage cathepsin L. Cathepsin L mediates the cleavage of the S1 subunit of the coronavirus surface spike glycoprotein." (PMID 33142828, 2020). "All these data indicate that CTSL might play an important role in COVID-19 pathogenesis in normal and cancer tissues of the lungs." (PMID 35414771, 2022). "scRNA-seq analysis comparing healthy controls and COVID-19 cases showed that CTSL expression was more abundant than ACE2 expression in placental trophoblast cells, and this transcription was increased in decidual stromal cells and antigen-presenting cells in COVID-19 pregnancies." (PMID 35492217, 2022).
COVID-19 (continued). "Although the proportion of SARS-CoV-2-positive cells in BALF was relatively similar, we found only two consensus genes from different cell types—one for the N gene of the virus and the other for the CTSL gene —when we compared the differential gene expression in COVID-19-positive to -negative cells." (PMID 34497809, 2021). "Indeed, soluble ACE2, TMPRSS2, and CTSL inhibitors have shown prominent antiviral effects and are potentially applicable in the prevention of SARS-CoV-2 infection and the treatment of COVID-19." (PMID 34471261, 2021). "The clinical data from this study indicated that human plasma CTSL activity and concentration were correlated with acute (in euglycemic participants under high-glucose clamp conditions) and chronic (in diabetic patients, both with and without COVID-19) hyperglycemia, respectively." (PMID 39150053, 2024). "The highest expression levels are found for Cathepsin L, followed by TLR4/MD-2 and TLR2 on macrophages and endothelial cells, whereas ~10fold lower expression levels are seen for TLR1, 6, and 7, which may correlate with the different pathophysiological relevance in COVID-19, as discussed later." (PMID 35682644, 2022). "We measured the plasma levels of COVID-19 related proteins, ACE2, CTSL, and CTSB in diabetic and non-diabetic COVID-19 patients." (PMID 39150053, 2024). "In our study, we evaluated plasma levels of ACE2, CTSL, and CTSB in COVID-19 patients with and without diabetes." (PMID 39150053, 2024). "Specially, the targets of the novel CPI such as AR, VDR, CTSL and Cathepsin B (CTSB) have been reported to be relevant for the treatment of COVID-19, thus these new predicted CPIs that have not been verified are good candidates for wet experiment exploration." (PMID 35275993, 2022). "In HNECs treated with HMGB1 and OSM, upregulation of the COVID-19-related genes TMPRSS6, furin, and cathepsin L (CTSL) was observed compared to the control, while no change of ACE2 or TMPRSS2 was observed." (PMID 34445093, 2021). "They reported significantly upregulated expression levels of cathepsins such as CTSL rather than of ACE2 in the lung, which has also been confirmed by others, suggesting the important role played by cathepsins in the increasing severity of COVID-19." (PMID 34471261, 2021). "For patients with COVID-19 who were not admitted to ICU, there was a statistically significant relationship between viral defense genes and CTSL expression, the four predictors (MX1, TRIM25 SAMHD1 and IFITM3) accounted for 65.56% of the variance (adjusted R2 = 0.656, p-value = 8.796–11)." (PMID 33633121, 2021).
breast carcinoma (40 papers, 2004 to 2026). "In breast cancer, increased expression of cathepsin B and cathepsin L is associated with poorer prognosis, greater mortality, and greater disease metastases." (PMID 38026637, 2023). "The lysosome-associated cysteine protease, cathepsin L, is often overexpressed in breast cancer and is believed to contribute to the dissemination of breast cancer cells." (PMID 31565189, 2019). "In summary, 1,25(OH)2D may protect against breast cancer by activating its receptor and inactivating the CTSL-mediated degradation of TP53BP1 in A-type lamin-deficient cells, which display BRCA1 deficiency, including cells with lost BRCA1." (PMID 32456160, 2020). "Here we identified the GRHL2 transcription factor as a chromatin recruiter of CTSL in KDM4C-amplified basal breast cancer cells." (PMID 40457074, 2025). "Taken together, these results identified the CTSL–GCLC axis as a key mediator of KDM4C-loss-associated metabolomic and epigenetic remodeling and tumor growth suppression in KDM4C-amplified basal breast cancer." (PMID 40457074, 2025). "KDM4C regulates cathepsin L-mediated histone H3 N-terminal tail clipping through grainyhead-like 2 (GRHL2) methylation in breast cancer." (PMID 40457074, 2025). "A considerable number of experiments have been performed to investigate the expression and role of cathepsin L in breast cancer." (PMID 36002710, 2023). "Inhibition of cathepsin L can also inhibit the EMT process of breast cancer cells mediated by TGF-β through Wnt signaling and PI3K-AKT signaling pathway–related Snail." (PMID 37398678, 2023). "Previous studies also support our findings with research implicating that nuclear CTSD and CTSL can also impact on cell cycle progression in breast cancer and colorectal cancer cell lines respectively." (PMID 38026973, 2023). "In conclusion, across a variety of breast cancer subtypes significant overexpression and amplified enzymatic activity of cathepsin L is observed, which increases with advancing grade and stage and has an important role during lung metastasis." (PMID 36002710, 2023). "It has also been established that breast cancer cells can maintain high cathepsin L levels, prioritizing its expression during stress conditions." (PMID 36002710, 2023). "In breast cancer, cathepsin L/X can also increase the activity of MDSCs in breast cancer and are related to breast cancer invasion." (PMID 37398678, 2023). "Cathepsin L is a lysosomal and extracellular endopeptidase whose expression is upregulated in breast cancer cells and TAMs, and which increases with advancing tumor grade." (PMID 36002710, 2023). "CTSL is a lysosomal enzyme, which has been demonstrated to be highly expressed in many malignant tumors such as lung cancer, breast cancer and cervical cancer." (PMID 36133820, 2022). "We used the MDA-MB-468 breast cancer cell line, which expresses moderate amounts of both EpCAM and CTSL." (PMID 33980181, 2021). "Analysis of the TCGA database showed that the expression of genes HPSE, PIK3AP1, SIGLEC7, LAIR1, and CTSL have positive correlations according to the breast cancer subtypes." (PMID 33053017, 2020). "The developed probe served as an effective imaging agent for cellular cathepsin L activity in human MDA-MB-231 breast cancer cells when incubated for 8 h." (PMID 32041276, 2020). "Overall, these data suggest that cathepsin L is a potential target to prevent macrophage-driven breast cancer invasion." (PMID 31565189, 2019). "Although CTSS expression was much higher than the expression of other cathepsins in TNBC cells, previous studies have shown that CTSB or CTSL regulates breast cancer invasion." (PMID 30185799, 2018). "Here, we utilized HyCoSuL, a positional scanning substrate approach, to develop a highly-selective fluorogenic substrate and activity-based probe for monitoring cathepsin L activity in the breast cancer cell line MDA-MB-231." (PMID 29719685, 2018).
breast carcinoma (continued). "Highly-selective fluorogenic substrate and activity-based probe for monitoring cathepsin L activity in the breast cancer cell line MDA-MB-231." (PMID 29719685, 2018). "Cathepsin L [EC 3.4.22.15] is secreted via lysosomal exocytosis by several types of cancer cells, including prostate and breast cancer cells." (PMID 26674348, 2015). "The presence of an active p110 CUX1 species carrying an HA tag in tumor samples and tumor-derived cell lines led us to assess cathepsin L expression in mammary tumors from MMTV-p200, p110, and p75 CUX1 transgenic mice." (PMID 24618719, 2014). "Both cathepsin L upregulation in breast cancer cells of different molecular subtypes and its partly extracellular localization make cathepsin L a suitable target for intraoperative fluorescence imaging of breast cancer." (PMID 36002710, 2023). "In vitro studies showed cathepsin L’s paracrine interaction with endothelial cells increases endothelial invasion, migration and sprouting while cathepsin L inhibition suppresses angiogenesis in xenograft breast cancer models." (PMID 36045675, 2022). "Furthermore, KD-1 was cell-permeable and inhibited the intracellular activity of cathepsin L in human MDA-MB-231 breast cancer cell lines." (PMID 32041276, 2020). "Because cathepsin L is expressed and secreted by both neoplastic and macrophage populations, its inhibition could be therapeutically beneficial for breast cancers with high macrophage infiltration." (PMID 31565189, 2019). "With these two types of libraries we were able to develop potent and highly selective fluorogenic substrates and ABPs for cathepsin L. Finally, we confirmed the utility of the identified probes by defining cathepsin L activity and localization in the breast cancer line MDA-MB-231." (PMID 29719685, 2018). "Targeting Cathepsin L (CTSL), whose upregulation is associated with poor clinical outcomes of breast cancer patients, may offer another approach that could be of significant benefit in the treatment of metastatic cancer patients." (PMID 29805773, 2018). "We plan to determine which of these isoforms is involved in the activation of cathepsin B. Additionally, we will explore the interplay of cathepsin L and cathepsin B activity in the extracellular space and their relative importance for breast cancer cell invasion." (PMID 28766149, 2017). "In these ten patient-matched breast cancer tissue specimens tested, cathepsin K activity was 50-fold higher than the activity in normal breast tissue (n = 10, p < .002), cathepsin L was 9-fold higher (n = 10, p < .005), and cathepsin S was 3-fold higher but not statistically significant." (PMID 21756348, 2011). "EpCAM c.344T>C may weaken protein folding, thereby promoting cervical cancer progression, enhance tumor cell stemness to facilitate breast cancer growth, and impair EpCAM’s inhibitory effect on cathepsin L, increasing the invasiveness of non-small cell lung cancer." (PMID 41164816, 2025). "Additionally, CTSL, which hydrolyzes T-DXd peptide ligators, is elevated in advanced breast cancer." (PMID 38794221, 2024). "Although the function of cathepsin L (Ctsl) in the complex process of tumorigenesis is not yet fully understood, the upregulation of its mRNA and protein levels especially in breast cancer correlates with a higher risk of relapse, poor therapy outcome, and worse overall survival." (PMID 32707827, 2020). "Thus our data suggest that tumor cells and macrophages may both contribute to the cathepsin L-driven metastatic phenotype of breast cancer." (PMID 31565189, 2019). "CTSL, CTSD, and HSPA8 were down-regulated in breast cancer cells, and their overexpression attenuated malignant behaviors of TNBC cells." (PMID 41399382, 2026). "In basal‐like breast cancer, inhibition of KDM4C promotes the recruitment of CTSL to chromatin through the transcription factor GRHL2." (PMID 41261048, 2025).